POLQ (DNA polymerase theta)
Diseases named in the same sentence as POLQ in open-access papers (continued):
Sharing a sentence is not in itself a finding about the gene and the disease.
cancer (continued). "Because DNA polymerase theta is highly expressed in many types of human cancers, our findings lay the groundwork for further investigations into how polymerase theta is involved in repair processes that may promote the development of cancer." (PMID 20617203, 2010). "Additionally, pan-cancer analysis was performed to confirm the importance of POLQ." (PMID 40735692, 2025). "Therefore, combination therapy with RECQL4 or PolQ inhibition could be a potential cancer therapy approach." (PMID 39870799, 2025). "Through subcutaneous tumor and peritoneal implantation models in nude mice, we found that POLQ inhibitors in combination with sulfasalazine synergistically exhibited anti-tumor effects, holding significant potential for direct translational applications in cancer therapy." (PMID 38575587, 2024). "While not essential for clonal escape from a telomere-driven crisis, POLQ activity evidently shapes the developing cancer genome, stimulating distinctive molecular interactions with identifiable sequelae that may be of value in the diagnosis or targeted treatment of cancer patients." (PMID 35774233, 2022). "Therefore, the inhibitors of PARP1 or POLQ block Alt-EJ pathway and kill HR-defective cancer cells." (PMID 35281059, 2022). "Hence, the absence of POLQ permits long-range telomere–centromere interactions akin to those implicated in cancer neochromosome formation." (PMID 35774233, 2022). "However, the mechanisms underlying the upregulation of POLQ expression, in particular in BRCA-deficient cancers, are still unknown." (PMID 34458275, 2021). "While ATM, BRCA, and POLQ mutations were similarly prevalent in both cancer types, adenocarcinoma patients had a high frequency to mutations effecting FANCM (8.9%) and FANCD2 (5.6%), comprising a majority of the difference between the two cancers in overall HR mutation rate." (PMID 33214570, 2020). "Interestingly, association of POLQ overexpression with increased somatic mutation load and PLK4 overexpression has been observed in other many cancer types, suggesting that POLQ overexpression may be involved in the pathogenesis of diverse human cancers." (PMID 31137743, 2019). "Interestingly, POLQ overexpression was associated with an increased somatic mutation load and PLK4 overexpression in diverse human cancers, while overexpressions of the nine TLS polymerases other than POLQ examined were associated with an increased somatic mutation load at much lower frequencies." (PMID 31137743, 2019). "Furthermore, six genes correlate with POLQ expression in the three different cancer types." (PMID 27612511, 2016). "Our analysis revealed 9 shared genes, with UBE2C, POLQ, RAD51, and HOXB7 being up-regulated and EDNRB, GPD1L, F10, SORBS2, and CXCL12 down-regulated in both cancers." (PMID 41790655, 2026). "Other anti-cancer strategies, such as RAD51 inhibitors, DNA-PKcs inhibitors, POLQ inhibitors, and berberine targeting the BER pathway are still under preclinical investigation." (PMID 39334297, 2024). "Interestingly, our results showed that the expression levels of CDK4, CDK6, and cyclin D1 in CRC cells were visually reduced after POLQ knockdown, which suggested that POLQ knockdown affects the cell cycle process and may be a potential factor in cancer therapy." (PMID 39520627, 2024). "We evaluated the expression level of POLQ via IHC analysis on a microarray slide containing 48 pairs of CRC tissues and para-carcinoma tissue, which showed prominent upregulation in CRC tissues (P < 0.01)." (PMID 39520627, 2024). "Although our findings demonstrate that STING is critical in the antitumor effects of POLQ inhibition in our model, STING activation has also been suggested to play a role in immune evasion in cancer." (PMID 36976649, 2023). "POLQ–/– clones derived from both HCT116 and HAP1 cancer cell lines presented telomere erosion and fusion rates comparable with WT cells, yet population growth deceleration during crisis was minimal." (PMID 35774233, 2022).
cancer (continued). "The disorders of polymerase theta (POLQ) were reported to contribute to GIN and progression in many cancers." (PMID 35726713, 2022). "In terms of cancer-related genes, novel recurrent CNAs were identified in PREX2 (8q gain) and POLQ (3q gain) in the peritoneal fluid, plasma, and tissue." (PMID 35626111, 2022). "More specific radiosensitization has been described for tumors overexpressing POLQ (also known as POL), a DNA polymerase that is error-prone and appears to provide a survival advantage for some cancers." (PMID 34746010, 2021). "Interestingly, POLQ expression is increased in cancers, both with and without HR deficiency." (PMID 34201502, 2021). "Accordingly, tumors with disrupted HR or NHEJ pathways, including BRCA1/2, rely on POLQ activity for DSB repair, and are sensitive to POLQ inhibition, PARP inhibition or cancer therapies introducing DSBs." (PMID 32885167, 2020). "Moreover, analysis of POLQ expression at the protein level has been performed in only a few cases; POLQ protein expression was analyzed in only one of the seven studies referred to above, so that it still remains unclear whether POLQ protein is also overexpressed in cancers." (PMID 31137743, 2019). "Finally, we investigated whether POLQ overexpression is observed in other types of human cancers." (PMID 31137743, 2019). "Notably, carboplatin significantly increased the expression of DNA damage repair-related genes, POLQ and RAD51, in cancer cells." (PMID 38740757, 2024). "As in addition to the classical NAB2-STAT6 fusion, we report four coding variants in cancer-associated genes (BIRC6, KIT, POLQ, and RBM10) which have not been previously reported in SFTs." (PMID 37469410, 2023). "Furthermore, the HRD group defined by our genomic signatures displays the characteristic features expected of such cancers, including MYC amplification and elevated POLQ expression." (PMID 37919776, 2023). "Other known and possibly yet undiscovered cancer mechanisms are captured by the SKY92, including cell cycle pathways (BIRC5, TOP2A, and CENPE), cell growth and proliferation (FGFR3), DNA repair (FANCF, FANCI, POLQ), and transcription factor (STAT1)." (PMID 34448362, 2022). "The impact of OxA treatment on chemoresistant tumors, on the expression of various proteins such as Nrf2, p-eIF2α, ATF4, PolQ, FoxM1, and Bcl2, which are involved in cancer chemoresistance, is not shown." (PMID 35747788, 2022). "The advent of novel pharmaceutical POLQ inhibitors combined with a burgeoning appreciation of the interactivity of DNAR pathways imparts renewed impetus to the management of residual and resistant disease in cancer." (PMID 35774233, 2022). "DDR genes including ATM, ATR, CHEK2, POLE, and POLQ could serve as potential biomarkers of ICI response, but their distinct and cancer-specific effects need to be investigated further." (PMID 34095878, 2021). "Further, our identified role for PolQ in mitosis is relevant to human cancer, as cancer cells lacking the BRCA2 or RAD52 repair proteins rely heavily on PolQ-mediated alt-EJ repair in mitosis." (PMID 34946831, 2021). "Since the circRNAs hsa_circ_0051620| SLC1A5 and hsa_circ_0066954| POLQ interact with CDH2, they might have a prognostic value in cancer." (PMID 34055888, 2021). "POLQ overexpression has been shown to be a negative prognostic indicator in human cancers, including breast cancer and ovarian carcinomas." (PMID 34746010, 2021). "Moreover, POLQ expression was further detected in 80 HCC tissues and 81 para-carcinoma tissues collected by our group." (PMID 34517891, 2021). "Our results also suggest that there might be POLQ-dependent and POLQ-independent MMEJ pathways in human cancer cells, both of which are suppressed by RPA." (PMID 27131361, 2016). "Finally, POLθ (DNA polymerase-theta) inhibitors (e.g., novobiocin) are in first-in-human studies for DDR-altered cancers and could be biologically attractive for HRD-like RCC subsets, but no results in RCC are available." (PMID 41440218, 2025).
cancer (continued). "However, why the over‐expression of POLQ was related to poor prognosis in cancer and the differential mechanisms between POLQ over‐expressing and suppressing cells were not clear." (PMID 35726713, 2022). "Moreover, POLQ is largely absent in most normal tissues, representing a promising tumor-specific target for cancer treatment." (PMID 34201502, 2021). "Among Cancer Gene Census genes, 1346 events were detected in 947 different loci, with the most recurrent ones being those in CLTCL1 (24 cases), CSMD3 (21 cases), MYH9 (20 cases), ANK1 (19 cases), TPR (19 cases), MYH11 (18 cases), PTPN13 (18 cases), and POLQ (17 cases)." (PMID 33809641, 2021). "However, the relative distribution of HR mutation among subtypes were varied, though all subtypes had relatively high rates of ATM, BRCA, and POLQ mutations, with FANCM mutations common to mucinous and non-specified carcinomas." (PMID 33214570, 2020). "Additionally, we examined whether concurrent overexpression of POLQ and PLK4, which was detected in LAC, is also observed in various other human cancers using the data of 17 cancer types from the TCGA database." (PMID 31137743, 2019).
tumor (54 papers, 2010 to 2026). "POLQ RNA abundances were also significantly higher in tumor versus normal samples linked to pathologic T-categories and closely associated with grade in two independent cohorts." (PMID 39166898, 2024). "Further study also demonstrated that high expression of POLQ was associated with tumour invasiveness." (PMID 39046429, 2024). "A level of POLQ was observed to be overexpressed in homologous-recombinant-deficient (HRD) tumours and was associated with a poorer outcome." (PMID 37190285, 2023). "While our data show that STING is required for tumor immune microenvironment changes and inhibition of tumor growth, we sought to determine if there was a contribution of the adaptive immune system to the antitumor phenotype observed with POLQ deficiency." (PMID 36976649, 2023). "Altogether, this indicates that POLQ inhibition induced DNA damage to ultimately trigger an influx of CD8+ T cells to suppress tumor growth in BRCA2-deficient PDAC, and STING represents a critical component of this pathway." (PMID 36976649, 2023). "More importantly, exciting novel findings from this study present new evidence linking the deficiencies of DNA damage repair genes (POLQ/FANCD2) with the activation of anti-tumor immunity through the cGAS-STING-STAT1 signaling pathway." (PMID 34206946, 2021). "Further taking tumor characteristics into account, we demonstrated that high POLQ expression was significantly associated with more lesion number, higher risk of tumor recurrence, and higher expression of ALT and GGT." (PMID 34517891, 2021). "Recent reports have demonstrated that POLQ inhibitors selectively kill HR-deficient tumour cells in vitro and in vivo." (PMID 34853396, 2021). "These all indicate the potential anti-tumor activation through a cGAS-STING-STAT1-mediated ISGs-involved pathway upon the loss of both POLQ and FANCD2 in ESCC." (PMID 34206946, 2021). "Further analysis revealed that high POLQ expression was linked to chromosome instability and higher tumor mutational burden (TMB), which might elicit the production of neoantigens." (PMID 38457207, 2024). "Moreover, the DNA polymerase theta inhibition approach harmonizes with PARPi activity in HR-deficient tumor elimination." (PMID 37783745, 2023). "Therefore, developing an inhibitor targeting DNA polymerase theta should be a rational option for curing HR-deficient tumor cells." (PMID 37783745, 2023). "Additionally, it has been demonstrated that POLQ knockdown sensitizes several tumour cell lines to Ionizing Radiation and causes minimal effects on normal tissue radiosensitivity." (PMID 34853396, 2021). "Therefore, POLQ inhibition strategies for tumors with POLQ overexpression and deficiency in HR are expected to sensitize tumor cells to radiotherapy while sparing normal tissue." (PMID 34746010, 2021). "To obtain new insights regarding the contextual relevance of Polθ overexpression in tumours, and identify possible mechanisms associated with its mode-of-action, we initially studied the correlation between the expression of POLQ and that of the genes involved either in DNA repair or replication." (PMID 27612511, 2016). "POLQ deficient mice show increased sensitivity to low doses of bleomycin in their bone marrow cells, and the same sensitivity has been observed in human tumor cells exposed to ionizing radiation." (PMID 25409685, 2014). "The co-expression of POLQ with genes linked to pathways associated with tumour progression, as well as several genes that are contained within the gene expression grade index, suggests that POLQ overexpression promotes a more aggressive phenotype, increasing the likelihood of disease recurrence." (PMID 20700469, 2010). "Larger studies are required to investigate whether the risk of relapse from tumours overexpressing cyclin E could be better assessed if further stratified by POLQ expression levels." (PMID 20700469, 2010).
tumor (continued). "In addition we have shown that tumours expressing both POLQ and CCNE2 are associated with an extremely poor outcome." (PMID 20700469, 2010). "However, the mechanism by which the DNA polymerase theta maintains synthetic lethality with HR-deficient tumors remains unclear, but this evidence suggests that the versatile functionality of the DNA polymerase theta is vital for HR-deficient tumor survival." (PMID 37783745, 2023). "Interestingly, tumor cells were more sensitive to POLQ inhibitors when the expression of 53BP1 in BRCA-deficient cells was reduced, suggesting that ART558 may resensitize patients with acquired resistance to PARPi by inhibiting DNA end excision protection." (PMID 36091750, 2022). "Having validated the effect of POLΘ inhibition in MCL using human cell lines, we next assessed the dependence on POLQ expression of primary tumor cells from patients with NHL." (PMID 40608419, 2025). "POLQ, which promotes cell proliferation and migration in HCC, is associated with tumor malignancy and poor prognosis." (PMID 39744494, 2025). "In this study they also analyzed the correlation between samples from patients with high POLQ expression in the IHC and the tumor recurrence or patient survival, finding that high POLQ expression in tumor samples predicted poorer prognosis." (PMID 39435280, 2024). "A significant discovery is that inhibiting POLQ in combination with PARPi can more effectively impair the survival capacity of tumor cells and compromise their DNA damage repair capability." (PMID 38270643, 2024). "The results revealed that in tumor tissues from ccRCC patients, POLQ expression positively correlated with the expression of CDC6, CDC45, CDT1, FANCD2, and MCM2." (PMID 38270643, 2024). "One challenge will be in the experimental evaluation of the combination of best affinity molecules and results in normal versus tumor cells where PolQ is more highly expressed." (PMID 39669672, 2024). "POLQ inhibition in combination with fractionated radiation has been shown to safely promote radiosensitization in tumor cells, while avoiding damage to normal cells, both in vitro and in vivo." (PMID 39166898, 2024). "POLQ inhibition represents a synthetic lethal approach to blocking tumor growth while concurrently activating the cGAS-STING signaling pathway, enhancing tumor immune infiltration and offering a novel therapeutic strategy." (PMID 39595558, 2024). "As DNA polymerase theta is synthetic and lethal with HR, inhibition of DNA polymerase theta in patients with defective HR can induce tumor cell death." (PMID 37783745, 2023). "The percentage of both CD8+ T cells and CD8+ granzyme B+ T cells were increased with POLQ knockdown, suggesting increased T cell–effector function in the tumor microenvironment in that setting." (PMID 36976649, 2023). "The tumor mutation burden (TMB) of these genes was also analyzed, and ASPM, CENPF, and POLQ had higher mutation rates than the other genes." (PMID 37077308, 2023). "Polymerase theta (POLQ or POLθ) is an A‐family DNA polymerases that is widely expressed in eukaryotes and is highly expressed in tumour cells and some normal human tissues." (PMID 35726713, 2022). "We found that POLQ suppression combined with etoposide treatment showed greater efficacy in reducing tumour growth compared with etoposide alone." (PMID 35726713, 2022). "We established xenografts in athymic mice using shPOLQ SACC‐LM and control cell lines, and treated mice with etoposide to determine the impact of altered POLQ expression on SACC tumours under DNA damage." (PMID 35726713, 2022). "According to the mechanism analysis, POLQ inhibitor induces tumor cell death from two aspects and seems to be a more promising drug." (PMID 36091750, 2022).